ABCG5 (ATP binding cassette subfamily G member 5)
Description:
ABCG5 and ABCG8 form an obligate heterodimer that mediates Mg(2+)- and ATP-dependent sterol transport across the cell membrane. Plays an essential role in the selective transport of dietary plant sterols and cholesterol in and out of the enterocytes and in the selective sterol excretion by the liver into bile. Required for normal sterol homeostasis. The heterodimer with ABCG8 has ATPase activity.
Synonyms: STSL; STSL2
Tractability: Small molecule: a structure with a bound ligand is known. Antibody: UniProt places it where antibodies can reach, with high confidence; its Gene Ontology location is reachable by antibodies, with high confidence; UniProt predicts a signal peptide or a membrane-spanning region. PROTAC: its protein half-life has been measured.
Gene: Protein-coding gene on chromosome 2 (43,812,472 to 43,838,865, reverse strand). Ensembl gene ENSG00000138075.
Subcellular location: Cell membrane; Apical cell membrane
Pathways (Reactome):
Disease: Defective ABCG5 causes sitosterolemia; Defective ABCG8 causes GBD4 and sitosterolemia
Signal Transduction: NR1H3 & NR1H2 regulate gene expression linked to cholesterol transport and efflux
Transport of small molecules: ABC transporters in lipid homeostasis
Gene Ontology:
Molecular function: ATP binding; ATP hydrolysis activity; ATPase-coupled transmembrane transporter activity; cholesterol transfer activity; protein binding; protein heterodimerization activity; ABC-type transporter activity; protein dimerization activity
Biological process: cholesterol efflux; cholesterol homeostasis; negative regulation of intestinal cholesterol absorption; negative regulation of intestinal phytosterol absorption; intestinal cholesterol absorption; sterol transport; lipid transport; response to ionizing radiation; response to muscle activity; response to nutrient; response to nutrient levels; response to xenobiotic stimulus; transmembrane transport; triglyceride homeostasis
Cellular component: apical plasma membrane; ATP-binding cassette (ABC) transporter complex; receptor complex; plasma membrane; apical part of cell; membrane
Genetic constraint (gnomAD): Loss-of-function variants: 58 observed, 59.23 expected, observed/expected ratio (o/e) 0.98, 90% interval 0.79 to 1.22. The upper end of that interval is the gene's LOEUF score, 1.22, which puts it in group 5 of 6, group 1 being the genes least tolerant of losing a copy. Missense variants: 821 observed, 740.28 expected, observed/expected ratio (o/e) 1.11, 90% interval 1.05 to 1.17. Synonymous variants: 354 observed, 298.41 expected, observed/expected ratio (o/e) 1.19, 90% interval 1.09 to 1.29.
Gene-disease validity (ClinGen):
ClinGen rates the evidence that ABCG5 causes each of these diseases.
sitosterolemia (autosomal recessive): Definitive. A rare autosomal recessive sterol storage disease characterized by the accumulation of phytosterols in the blood and tissues.
Homologues: Orthologues: chimpanzee ABCG5 (99% identical), macaque ABCG5 (94% identical), dog ABCG5 (85% identical), pig ABCG5 (84% identical), mouse Abcg5 (80% identical), rat Abcg5 (79% identical), rabbit ABCG5 (75% identical), tropical clawed frog abcg5 (60% identical), zebrafish abcg5 (59% identical), guinea pig ABCG5 (58% identical), Drosophila melanogaster CG11069 (25% identical), Caenorhabditis elegans abch-1 (21% identical). Paralogues in human: ABCG4 (27% identical), ABCG1 (25% identical), ABCG8 (25% identical), ABCG2 (24% identical).
Diseases named in the same sentence as ABCG5 in open-access papers:
ABCG5 is named in the same sentence as 75 diseases in open-access papers, as found by Europe PMC text mining. Sharing a sentence is not in itself a finding about the gene and the disease. The quoted sentences say what the papers report.
sitosterolemia (78 papers, 2004 to 2026). "Sitosterolemia is a rare autosomal recessive lipid metabolic disorder caused by mutations in ABCG5 or ABCG8, leading to pathological accumulation of dietary plant sterols." (PMID 42111500, 2026). "Previous studies have suggested that most Chinese probands with sitosterolemia have mutations in the ABCG5 gene, whereas mutations in the ABCG8 gene are more prevalent among probands of Caucasian origin." (PMID 39860331, 2025). "Among Vietnamese patients with sitosterolemia, ABCG5 gene variants were more common than ABCG8 gene variants." (PMID 39860331, 2025). "In our study, the diagnosis of sitosterolemia in 14 patients was confirmed based on the presence of disease-causing variants in the ABCG5 or ABCG8 genes, along with elevated levels of TC and LDL-C." (PMID 39860331, 2025). "Treatment is different for people with sitosterolemia due to ABCG5/ABCG8 pathogenic variants that cause severe hypercholesterolemia and ASCVD and can phenocopy FH." (PMID 40004987, 2025). "Although ABCG5/G8-deficient animal models recapitulate the symptoms of sitosterolemia, including hematologic abnormalities and organ dysfunction, increased atherogenicity has not been observed in these models." (PMID 41118071, 2025). "We treated 2 patients with ABCG5 mutations and sitosterolemia with ezetimibe to reduce cholesterol and plant sterol absorption, leading to the normalization of thrombocytopenia, peripheral smear findings, and hemolytic anemia." (PMID 40488176, 2025). "Phytosterolemia is a rare AR disorder caused by biallelic ABCG5 or ABCG8 mutations, leading to phytosterol accumulation." (PMID 40941697, 2025). "Clinical features of sitosterolemia due to ABCG5 mutations included elevated plant sterol levels, xanthomas, premature atherosclerosis, hemolytic anemia (stomatocytosis), and macrothrombocytopenia." (PMID 40488176, 2025). "Bi-allelic genetic loss of ABCG5/8 causes sitosterolemia, which is characterized by high plasma phytosterols, hypercholesterolemia, xanthomata, premature atherosclerosis, and hematological sequelae." (PMID 40004987, 2025). "The molecular pathogenesis of sitosterolemia results from biallelic mutations affecting the ABCG5 or ABCG8 genes, these two genes encode ATP-binding cassette transporters critical for regulating intestinal absorption and biliary excretion of plant sterols." (PMID 41170196, 2025). "Within the Chinese population with sitosterolemia, nearly half of the patients with ABCG5 variants exhibit the R446X variant, which is the most common variant in this population." (PMID 39039599, 2024). "This study identified two heterozygous variants in the ABCG5 gene, specifically c.1336C>T and a novel variant c.1800T>A, confirming the diagnosis of sitosterolemia." (PMID 39055399, 2024). "The recognized cause of sitosterolemia is homozygous or compound heterozygous mutations in the ABCG5 and ABCG8 genes leading to a loss of function of the adenosine triphosphate (ATP)-binding cassette." (PMID 39055399, 2024). "These conditions include sitosterolemia (or “phytosterolemia”), which results from biallelic rare pathogenic variants in the ATP-binding cassette transporter genes ABCG5 and/or ABCG8." (PMID 40896709, 2024). "Sitosterolemia is considered an extremely rare recessive disorder caused by pathogenic variants in ABCG5 or ABCG8 in both alleles." (PMID 38540356, 2024). "The presence of xanthomas on the skin and tendons, hypercholesterolemia, and significantly elevated phytosterol levels in the patients, combined with the presence of ABCG5 gene variants, met the diagnostic criteria for sitosterolemia." (PMID 39039599, 2024). "Sitosterolemia is a rare inherited lipid disorder caused by the loss of the sterol transporter ABCG5/G8 (sterolin)." (PMID 39566847, 2024). "Previous studies have indicated that most Asian sitosterolemia patients, particularly Chinese or Japanese individuals, harbor the ABCG5 variant, whereas Caucasians harbor the ABCG8 variant." (PMID 39039599, 2024).
sitosterolemia (continued). "Type 2 sitosterolemia (ABCG5) or type 1 sitosterolemia (ABCG8) gene variations are the cause of sitosterolemia, and the ABCG5 and ABCG8 transporter proteins are highly expressed in the human liver and small intestine." (PMID 38509578, 2024). "It is estimated that at least 1 in 200,000 people in the general population have sitosterolemia caused by pathogenic variants in ABCG5 or ABCG8." (PMID 38540356, 2024). "Almost all ABCG5/ABCG8 loss-of-function variants identified in our cohort have been reported before in patients with sitosterolemia providing evidence to be classified as pathogenic or likely pathogenic." (PMID 38122934, 2023). "Even in the case of homozygous or combined heterozygous mutations of the ABCG5/G8 transporter, such as in phytosterolemia, PS plasma concentrations remain at about 0.3–1.2 mmol/L (approx. 12–48 mg/dL)." (PMID 36839186, 2023). "ABCG5/8 is the pathogenic genes associated with sitosterolemia, characterized by increasing levels of plant sterols." (PMID 36991406, 2023). "In an analysis of the genetic causes of sitosterolemia in 33 families from different ethnic populations, all six Japanese probands appeared to have mutations in ABCG5 only." (PMID 36981027, 2023). "Phytosterolemia is caused by homozygous or compound heterozygous defects in the genes ABCG5/sterolin-1 and ABCG8/sterolin-2 on chromosome 2p21." (PMID 36839186, 2023). "Sitosterolemia is a lipid disorder characterized by the accumulation of phytosterols in plasma and organs, caused by mutations in the ABCG5 and/or ABCG8 genes." (PMID 35042526, 2022). "In people with sitosterolemia, a rare recessive disease characterized by mutations of the ABCG5 or ABCG8 transporter genes, the levels of PS can increase excessively from 30 to 100 times higher compared to normal values, especially in heterozygous subjects." (PMID 36432457, 2022). "They named their new lipid disorder β-sitosterolemia (hereon referred to as sitosterolemia), but it would be another 26 years before the discovery of ABCG5 ABCG8 as the causative gene defect." (PMID 33807969, 2021). "Phytosterolemia caused by deleterious mutations within the ABCG5/8 heterodimeric transporter is estimated to affect more than 1 in 200,000 individuals within the general population." (PMID 34465831, 2021). "Its function is essential as rare ABCG5/8 loss of function variants cause phytosterolemia and increase the risk of developing coronary artery disease, experiencing a myocardial infarction or sudden cardiac death." (PMID 34465831, 2021). "Deficiency of ABCG5 or ABCG8 in sitosterolemia impairs excretion of plant sterol into the intestinal lumen from enterocytes and into bile in the liver, thereby resulting in a severe accumulation of plant sterols in plasma and tissues." (PMID 35096999, 2021). "Patient 46-1, who had 17% of stomatocytes at peripheral blood smear without any abnormality of the Osmoscan curve, was diagnosed with sitosterolemia due to ABCG5 mutation p.Y458X." (PMID 34093240, 2021). "The remaining new variants were identified in enzyme genes (PKLR: p.R531S; HK1: p.R12X, p.G451R; NT5C3A: p.R22X), and in genes associated with sitosterolemia (ABCG5: p.Y458X) and sideroblastic anemia (ALAS2: p.H524R)." (PMID 34093240, 2021). "Other mutations to these positions are found as variants in vivo, some causing sitosterolemia, such as mutations to E146 in ABCG5, analogous to E138 in ABCG2." (PMID 33809494, 2021). "ABCG5 or ABCG8 gene have been shown to be associated with LDL cholesterol level through common genetic variations as well as rare variations leading to sitosterolemia, a recessive Mendelian disorder." (PMID 31901240, 2020). "In sitosterolemia, pathogenic variants in the ABCG5 or ABCG8 genes result in defective ABCG5/ABCG8 efflux transporters, resulting in pathologically high absorption rates of sitosterol (15–60%)." (PMID 32845916, 2020).
sitosterolemia (continued). "Cholesterol is secreted via the heterodimer transporter ABCG5/ABCG8 (genes ABCG5/ABCG8) also called sterolin, and mutations in ABCG5/ABCG8 genes can cause sitosterolemia, which has a varied clinical presentation including associated liver disease." (PMID 32432119, 2020). "Sitosterolemia is an extremely rare autosomal recessive disease caused by mutations in either ABCG5 or ABCG8, which encode for a sterol efflux transporter (sterolin) that pumps sterols out into the intestinal lumen or into bile." (PMID 33204594, 2020). "In the pathogenic circumstances of sitosterolemia, variants in the ABCG5 or ABCG8 genes lead to reduced sitosterol excretion, consequently resulting in increased absorption of sitosterol." (PMID 32845916, 2020). "The pathogenesis of sitosterolemia is defined by pathogenic variants in either the ABCG5 and/or ABCG8 genes, which results in increased intestinal absorption and decreased biliary extraction of plant sterols." (PMID 32845916, 2020). "Missense mutations of ABCG5/G8 can cause sitosterolemia, a loss-of-function disorder characterized by plant sterol accumulation and premature atherosclerosis." (PMID 33228147, 2020). "This suggests a more profound impact of sitosterolemia mutations on the ABCG5/G8 ATPase activity through sterol–protein interaction or structural changes." (PMID 33228147, 2020). "Mutations in human ABCG5 or ABCG8 cause sitosterolemia, a disease characterized by increased absorption and decreased biliary excretion of dietary phytosterols such as the common plant sterol β-sitosterol." (PMID 33575564, 2020). "Researchers including ourselves have shown the great effectiveness of ezetimibe in the case of sitosterolemia who has double mutations in ATP-binding cassette sub-family G member 5 or 8 (ABCG5) or (ABCG8) gene." (PMID 31901240, 2020). "Inactivation of either ABCG5 or ABCG8 causes sitosterolemia, a genetic disorder characterized by sterol accumulation and premature coronary atherosclerosis." (PMID 30679232, 2019). "Mutations in ABCG5 or ABCG8 genes cause sitosterolemia, in which patients present increased LDL-C levels, some characteristic FH phenotype features and higher cardiovascular risk, alike FH." (PMID 30388787, 2018). "Decades ago, the first report on a syndrome now known as sitosterolemia appeared, which later on was linked to mutations in the ABCG5 and ABCG8 genes leading to loss of function of the ABCG5/G8 transporter." (PMID 28383515, 2017). "Sitosterolemia is a rare autosomal recessive condition caused by mutations in two other ABC transporters: ABCG5, and ABCG8." (PMID 22649448, 2012). "Segregation analysis showed that the inheritance of the Gly583Cys mutation Abcg5 segregated with elevated plant sterols and this pattern was recessive, proving that this genetic change is responsible for the sitosterolemia in these rat strains." (PMID 16026620, 2005). "Although ABCG5/8 genes cause autosomal recessive sitosterolemia, heterozygous carriers of ABCG5/8 variants may have a small effect on elevating LDL-C levels, resulting in a less severe hypercholesterolemic phenotype." (PMID 40517278, 2025). "Phytosterolemia or sitosterolemia is solely associated with ABCG5/G8 mutations." (PMID 40004982, 2025). "In addition, we can assume that patients whose serum sitosterol level is 10 μg/mL or more are highly likely to have sitosterolemia and have deleterious ABCG5 or ABCG8 variants in both alleles." (PMID 38540356, 2024).
sitosterolemia (continued). "It is worth noting that the increased phytosterol in cases of elevated HDL-C elicited by the CETP inhibitor Dalcetrapib was similar to that seen with statin treatment, and different from that measured in ABCG5/G8 mutation leading to atherogenic phytosterolemia." (PMID 35299760, 2022). "Hence, this population-based work along with segregation of an ABCG5 variant in a large pedigree with sitosterolemia identifies heterozygosity for specific ABCG5 variants as an additional genetic cause of macrothrombocytopenia." (PMID 34880906, 2021). "Nonetheless, this classification system provides a framework for characterizing ABCG5 ABCG8 mutants that cause sitosterolemia and a basis for the systematic investigation of compounds that may potentially rescue G5G8 function." (PMID 33807969, 2021). "WGS analysis identified compound heterozygous variants in ABCG5 responsible for abnormal cholesterol excretion consistent with the known disorder sitosterolemia, which supported our hypothesis." (PMID 34880906, 2021). "Loss-of-function mutations in either ABCG5 or ABCG8 have been identified as a cause of sitosterolemia, a rare autosomal recessive disorder characterized by elevated plasma levels of plant sterols due to increased intestinal absorption of dietary sitosterol and decreased biliary sterol secretion." (PMID 34173968, 2021). "Loss-of-function (LOF) mutations in ABCG5 or ABCG8 are linked to sitosterolemia, a rare autosomal recessive disease, while several other missense mutations are also associated with other lipid disorders, such as gallstone formation or elevated low-density lipoprotein (LDL) cholesterol." (PMID 33228147, 2020). "Indeed, mutations in ABCG5/8 genes lead to an accumulation of plant sterols in the body, mainly sitosterol, causing a disease condition called sitosterolemia." (PMID 30388787, 2018). "Mutations in human genes encoding for ABCG5 or ABCG8 have been demonstrated to cause sitosterolemia, characterized by an accumulation of sterols in blood and tissues, consequent to the enhanced intestinal absorption and decreased biliary removal of CH and plant sterols." (PMID 29420298, 2018). "Moreover, homozygous or compound heterozygous mutations in either ABCG5 or ABCG8 were observed in patients with sitosterolemia, an inborn error of metabolism." (PMID 29949603, 2018). "Mutations in ABCG5 or ABCG8 in sitosterolemic patients characterized by extremely high circulating sitosterol might explain the proatherogenic effects of sitosterolemia." (PMID 22412917, 2012). "Although phytosterolemia, as recessive genetic disease related to deficiency of ABCG5/G8 carriers, is very rare, mild to moderate increases in phytosterolemia may be associated with increased cardiovascular risk, although this topic is still controversial." (PMID 21810257, 2011). "To determine the role of the Abcg5/Abcg8 heterodimer in the plant sterol-induced stimulation of fecal neutral sterol output, we performed similar experiments in the Abcg5-deficient mouse, an animal model for sitosterolemia." (PMID 21738715, 2011). "Two mutations in either both copies of ABCG5 or both copies of ABCG8 result in sitosterolemia." (PMID 16507104, 2006). "In addition to ABCG5/8 (Adenosine triphosphate-binding cassette subfamily G members 5 and 8) genes causing sitosterolemia, which is considered FH phenocopy and may mimic FH." (PMID 40517278, 2025). "While low PS plasma concentrations in healthy individuals are primarily a result of normal intestinal ABCG5/G8 action, autosomal recessive mutations in ABCG5/G8 lead to rare phenotypes in individuals characterized by excess concentrations of circulatory PS, a condition known as sitosterolemia." (PMID 37764302, 2023). "In humans, mutations of ABCG5/G8 may cause autosomal recessive sitosterolemia." (PMID 36981027, 2023).